RGS7BP (regulator of G protein signaling 7 binding protein)
Description:
Regulator of G protein-coupled receptor (GPCR) signaling. Regulatory subunit of the R7-Gbeta5 complexes that acts by controlling the subcellular location of the R7-Gbeta5 complexes. When palmitoylated, it targets the R7-Gbeta5 complexes to the plasma membrane, leading to inhibit G protein alpha subunits. When it is unpalmitoylated, the R7-Gbeta5 complexes undergo a nuclear/cytoplasmic shuttling. May also act by controlling the proteolytic stability of R7 proteins, probably by protecting them from degradation.
Synonyms: R7BP
Tractability: Antibody: UniProt places it where antibodies can reach, with medium confidence; its Gene Ontology location is reachable by antibodies, with medium confidence. PROTAC: its protein half-life has been measured.
Gene: Protein-coding gene on chromosome 5 (64,506,015 to 64,612,319, forward strand). Ensembl gene ENSG00000186479.
Subcellular location: Nucleus; Cytoplasm; Cell membrane
Subcellular location (Human Protein Atlas): Cytosol; Plasma membrane; Actin filaments
Gene Ontology:
Biological process: G protein-coupled receptor signaling pathway; regulation of postsynaptic membrane potential
Cellular component: cytoplasm; neuron projection; nucleus; plasma membrane; postsynapse; axon; dendritic shaft; dendritic spine head; glutamatergic synapse; perikaryon; postsynaptic density membrane; presynapse; presynaptic membrane
Genetic constraint (gnomAD): Loss-of-function variants: 8 observed, 24.25 expected, observed/expected ratio (o/e) 0.33, 90% interval 0.19 to 0.6. The upper end of that interval is the gene's LOEUF score, 0.6, which puts it in group 2 of 6, group 1 being the genes least tolerant of losing a copy. Missense variants: 230 observed, 271.6 expected, observed/expected ratio (o/e) 0.85, 90% interval 0.76 to 0.94. Synonymous variants: 91 observed, 103.46 expected, observed/expected ratio (o/e) 0.88, 90% interval 0.74 to 1.05.
Homologues: Orthologues: chimpanzee RGS7BP (99% identical), macaque RGS7BP (99% identical), dog RGS7BP (98% identical), pig RGS7BP (98% identical), guinea pig RGS7BP (97% identical), rabbit RGS7BP (96% identical), rat Rgs7bp (96% identical), mouse Rgs7bp (95% identical), tropical clawed frog rgs7bp (80% identical), zebrafish rgs7bpa (72% identical), zebrafish rgs7bpb (70% identical), Drosophila melanogaster CG14340 (22% identical), and 1 more. Paralogues in human: RGS9BP (17% identical).
Diseases named in the same sentence as RGS7BP in open-access papers:
RGS7BP is named in the same sentence as 7 diseases in open-access papers, as found by Europe PMC text mining. Sharing a sentence is not in itself a finding about the gene and the disease. The quoted sentences say what the papers report.
epilepsy (1 paper, 2020). A brain disorder characterized by episodes of abnormally increased neuronal discharge resulting in transient episodes of sensory or motor neurological dysfunction, or psychic dysfunction. "The overall results favor the view that CSMD1, STIM2, and RGS7BP genes could contribute to epilepsy and migraine phenotypes in our family." (PMID 32315120, 2020). "Array CGH study also disclosed that the three affected individuals carried a rare deletion at 5q12.3 that partially involves the RGS7BP gene, while mutations in genes mostly associated with both epilepsy and migraine were ruled out." (PMID 32315120, 2020). "Thus, considering the oligogenic origin of epilepsies, it is reasonable to speculate that the detrimental effect of the rearrangement on CSMD1 and hypothetically STIM2, together with RGS7BP deletion may contribute to the epilepsy/migraine phenotypes in our family." (PMID 32315120, 2020).
Hypertension (1 paper, 2018). The presence of chronic increased pressure in the systemic arterial system. "The result showed that miR-124a might be involved in the pathogenesis of hypertension via targeting Ebf3 and Rgs7bp, which possibly serves as a novel and effective strategy for the treatment of hypertension." (PMID 30648107, 2018).
infectious disease (1 paper, 2023). A disorder directly resulting from the presence and activity of a microbial, viral, or parasitic agent in humans. "RGS7BP is highly expressed in blood vessels and plays a role in infectious disease pathogenesis." (PMID 36972313, 2023).
RGS7BP also shares sentences with these, for which no sentence is quoted: eczema (1 paper); itch (1); migraine (1); neuropathies (1).